TRIP12 (thyroid hormone receptor interactor 12)
Description:
E3 ubiquitin-protein ligase involved in ubiquitin fusion degradation (UFD) pathway and regulation of DNA repair. Part of the ubiquitin fusion degradation (UFD) pathway, a process that mediates ubiquitination of protein at their N-terminus, regardless of the presence of lysine residues in target proteins. Acts as a key regulator of DNA damage response by acting as a suppressor of RNF168, an E3 ubiquitin-protein ligase that promotes accumulation of 'Lys-63'-linked histone H2A and H2AX at DNA damage sites, thereby acting as a guard against excessive spreading of ubiquitinated chromatin at damaged chromosomes. In cancer cells, however, isoform p19ARF/ARF and TRIP12 are located in different cell compartments, preventing isoform p19ARF/ARF ubiquitination and degradation. Does not mediate ubiquitination of isoform p16-INK4a of CDKN2A. Also catalyzes ubiquitination of NAE1 and SMARCE1, leading to their degradation. Ubiquitination and degradation of target proteins is regulated by interaction with proteins such as MYC, TRADD or SMARCC1, which disrupt the interaction between TRIP12 and target proteins. Mediates ubiquitination of ASXL1: following binding to N(6)-methyladenosine methylated DNA, ASXL1 is ubiquitinated by TRIP12, leading to its degradation and subsequent inactivation of the PR-DUB complex.
Synonyms: ULF; TRIP-12; KIAA0045; TRIPC; MRD49
Tractability: Small molecule: a structure with a bound ligand is known. PROTAC: ubiquitination databases record sites on it; its protein half-life has been measured.
Gene: Protein-coding gene on chromosome 2 (229,763,835 to 229,923,239, reverse strand). Ensembl gene ENSG00000153827.
Subcellular location: Nucleus, nucleoplasm
Subcellular location (Human Protein Atlas): Nuclear speckles
Pathways (Reactome):
Immune System: Antigen processing: Ubiquitination & Proteasome degradation
Gene Ontology:
Molecular function: nuclear thyroid hormone receptor binding; protein binding; ubiquitin protein ligase activity; ubiquitin-protein transferase activity; zinc ion binding
Biological process: DNA repair-dependent chromatin remodeling; heterochromatin boundary formation; protein polyubiquitination; ubiquitin-dependent protein catabolic process; DNA damage response; proteasome-mediated ubiquitin-dependent protein catabolic process; regulation of embryonic development; protein ubiquitination
Cellular component: nucleoplasm; nucleus; cytosol
Genetic constraint (gnomAD): Loss-of-function variants: 24 observed, 232.27 expected, observed/expected ratio (o/e) 0.1, 90% interval 0.074 to 0.14. The upper end of that interval is the gene's LOEUF score, 0.14, which puts it in group 1 of 6, group 1 being the genes least tolerant of losing a copy. Missense variants: 1,650 observed, 2,526.1 expected, observed/expected ratio (o/e) 0.65, 90% interval 0.63 to 0.68. Synonymous variants: 891 observed, 894.38 expected, observed/expected ratio (o/e) 1, 90% interval 0.94 to 1.05.
Gene-disease validity (ClinGen):
ClinGen rates the evidence that TRIP12 causes each of these diseases.
complex neurodevelopmental disorder (autosomal dominant): Definitive. A disorder that involves more than one phenotype associated with the central nervous system, including but not limited to intellectual disability, autism, and seizures (epilepsy).
Homologues: Orthologues: chimpanzee TRIP12 (99% identical), dog TRIP12 (99% identical), rat Trip12 (98% identical), macaque TRIP12 (98% identical), pig TRIP12 (98% identical), rabbit TRIP12 (97% identical), mouse Trip12 (96% identical), guinea pig TRIP12 (92% identical), tropical clawed frog trip12 (90% identical), zebrafish trip12 (83% identical). Paralogues in human: HECTD1 (24% identical), HECTD4 (20% identical), HECW2 (10% identical), HUWE1 (10% identical), HECW1 (10% identical), HERC2 (10% identical), ITCH (10% identical), WWP1 (9% identical), WWP2 (9% identical), HERC4 (9% identical), UBR5 (9% identical), HERC3 (8% identical), and 12 more.
Diseases named in the same sentence as TRIP12 in open-access papers:
TRIP12 is named in the same sentence as 44 diseases in open-access papers, as found by Europe PMC text mining. Sharing a sentence is not in itself a finding about the gene and the disease. The quoted sentences say what the papers report.
breast carcinoma (7 papers, 2021 to 2025). "Given the association between TRIP12 expression and tumorigenesis, we investigated the biological function of TRIP12 in breast cancer." (PMID 36639831, 2023). "In this study, using publicly available cancer patient datasets, we found TRIP12 to be associated with distant metastasis-free survival in breast cancer, suggesting an inhibitory role in metastasis." (PMID 33963176, 2021). "Among different clinical parameters and different cancers, we observe that level of TRIP12 is positively associated with distant metastasis-free survival of breast cancer patients." (PMID 33963176, 2021). "We evaluated the impact of TRIP12 on the apoptosis capabilities of breast cancer cells by flow cytometry and a caspase‐3 activity assay." (PMID 36639831, 2023). "TRIP12 inhibition increased the metastasis of MDA-MB-231 breast cancer cells compared to the controls." (PMID 37863914, 2023). "Lastly, distant metastasis-free survival is lower (p value = 0.03563; COX p value = 0.26621; HR = 0.70(95% CI: 0.37–1.32)) in TRIP12 low tumors than in TRIP12 high tumors in the GSE7390 breast cancer study." (PMID 33963176, 2021). "Distant metastasis-free survival is significantly lower (COX p value = 0.01819; HR = 0.20(95% CI: 0.05–0.76)) in breast cancer patients with low TRIP12 as compared to high TRIP12 levels in the GSE11121 study." (PMID 33963176, 2021). "Interestingly, MCL-1 amplifications are more frequent in breast cancer compared to colorectal or ovarian cancer which will ultimately nullify the impact of TRIP12 inhibition in those cells." (PMID 36672454, 2023). "A study on breast cancer showed that TRIP12 suppresses EMT via ZEB1/2." (PMID 37573347, 2023). "Next, we tested whether the depletion of TRIP12 in breast cancer cells could achieve similar synergy with Taxol as witnessed with ovarian cancer cells." (PMID 36672454, 2023). "Finally, CRISPR/Cas9 mediated genetic targeting of TRIP12 in MDA-MB-231 breast cancer cells enhances the TGFβ induced migratory capacity of these cells which was rescued to the wildtype level by re-introducing wildtype TRIP12." (PMID 37863914, 2023). "Additionally, TRIP12 regulates response to PARP inhibitors in breast cancer cells and we have shown that the genetic inhibition of TRIP12 leads to the stabilisation of FBW7 protein, mitotic arrest, and enhanced cell death in response to Taxol treatment." (PMID 37863914, 2023). "Interestingly, TRIP12 regulates response to PARP inhibitors in breast cancer cells and we have shown that the genetic inhibition of TRIP12 leads to the stabilization of FBW7 protein and enhanced cell death in response to Taxol treatment." (PMID 36672454, 2023). "Furthermore, we examined the effect of TRIP12 on the migration capacity of breast cancer cells." (PMID 36639831, 2023). "Overall, our study delineates TRIP12’s role in inhibition of EMT and implies a potential suppressive role in breast cancer metastasis." (PMID 33963176, 2021). "However, this genetic interaction was not seen in breast cancer cells because TRIP12 inhibition in those cells did not enhance Taxol-mediated cell death." (PMID 36672454, 2023). "Finally, the TRIP12/FBW7/MCL-1 axis is well preserved in ovarian cancer but not in breast cancer cells since siRNA-mediated depletion of TRIP12 sensitized those cells to Taxol in an FBW7-dependent manner." (PMID 36672454, 2023). "Finally, TRIP12 deletion leads to enhanced mitotic arrest and cell death in an FBW7 and MCL-1 dependent manner in multiple cell lines including colorectal and ovarian cancer but not in breast cancer." (PMID 36672454, 2023).
developmental delay (5 papers, 2020 to 2025). "Pathogenic variants in TRIP12 are often associated with neurodevelopmental disorders, such as developmental delay and intellectual disability." (PMID 37880672, 2023). "Across all variant classes, the most recurrent clinical features include intellectual disability, autism spectrum disorder, developmental delay and marked speech impairment, consistent with the core neurodevelopmental phenotype associated with TRIP12 dysfunction." (PMID 41465129, 2025). "Notably, heterozygous models of TRIP12 deficiency have also shown phenotypes, including developmental delay and abnormal placental morphology." (PMID 39135741, 2024). "Our SVM classification model showed that the episignature was highly specific and sensitive, and confirmed that TRIP12 biomarkers could be differentiated from other EpiSignTM disorders associated with developmental delay and intellectual disability." (PMID 36430143, 2022). "Clinical features such as developmental delay, hearing loss, and epilepsy in our patients could be attributed to TRIP12 haploinsufficiency." (PMID 32528716, 2020). "Both USP7 and TRIP12 pathogenic variations have been associated with a spectrum of neurological and developmental abnormalities, sharing overlapping features such as intellectual disability, developmental delay, motor delay, speech delay, facial dysmorphisms, and growth abnormalities." (PMID 39135741, 2024). "Here, we describe a case of a 4-year-old boy with a de novo 2q36.3q37.1 deletion encompassing TRIP12 and NPPC who presented with severe developmental delay, extremely short stature, small hands, dysmorphic facial features, hearing loss, and epilepsy." (PMID 32528716, 2020). "Thus, genes other than TRIP12 and NPPC located in the deletion region might have contributed to the exaggerated phenotypes in terms of developmental delay and short stature." (PMID 32528716, 2020).
acute myeloid leukemia (4 papers, 2020 to 2021). Acute myeloid leukemia (AML) is a group of neoplasms arising from precursor cells committed to the myeloid cell-line differentiation. "A RNA-seq analysis of 139 patients with pediatric Acute Myeloid Leukemia (AML) revealed the existence in one patient of a new gene rearrangement leading to the fusion between TRIP12 and NPM (nucleophosmin) proteins." (PMID 33198194, 2020).
Intellectual disability (4 papers, 2021 to 2025). "Subsequent studies have shown that de novo or inherited TRIP12 variants cause variable intellectual disability, autism spectrum disorder (ASD), epilepsy, and sometimes dysmorphic traits." (PMID 41465129, 2025). "Intellectual disability is reported in 100% of individuals with pathogenic TRIP12 variants, with cognitive performance ranging from mild to severe." (PMID 41465129, 2025). "Haploinsufficiency of TRIP12 has been reported to cause childhood-onset neurodevelopmental disorder including intellectual disability, as important information cannot be obtained by ultrasound diagnosis alone." (PMID 37880672, 2023). "Apart from cancer, recurrent TRIP12 mutations occur frequently in patients with neurodevelopmental diseases exhibiting symptoms of autism spectrum disorder, intellectual disability, and craniofacial dysmorphism." (PMID 33963176, 2021). "Thus, pathogenic variants in TRIP12 result in dysfunction of the ubiquitin pathway which, in turn, leads to a wide range of disorders, including intellectual disability, cancer and neurodegenerative diseases such as Parkinson’s and Alzheimer disease." (PMID 36430143, 2022). "Case 21 with the c.2482C>G p.(Pro828Ala) variant had obesity and mild intellectual disability, features which are not unique for TRIP12 variants." (PMID 36430143, 2022).
autism (3 papers, 2020 to 2025). Persistent deficits in social interaction and communication and interaction as well as a markedly restricted repertoire of activity and interest as well as repetitive patterns of behavior. "Finally, Trip12 is an E3 ubiquitin ligase with rare loss-of-function mutations implicated in cognitive deficits and autism." (PMID 38542311, 2024). "The Trip12 gene is a high confidence gene for autism in the SFARI GENE database (see Section Software and databases)." (PMID 33198194, 2020). "Pathogenic TRIP12 variants are now documented in gene variant databases related to human health LOVD (Leiden Open Variation Database (see Section Software and databases)) and ClinVar (Clinical Variation (see Section Software and databases)) and can be also found in ID/autism websites." (PMID 33198194, 2020).
autism spectrum disorder (3 papers, 2020 to 2025). A spectrum of developmental disorders that includes autism, and Asperger syndrome. "The TRIP12 gene is also referenced as a causative gene associated to intellectual disorders such as Clark–Baraitser syndrome and is clearly implicated in Autism Spectrum Disorder." (PMID 33198194, 2020). "Mutual comorbidities of ID and Autism Spectrum Disorder (ASD) also raised the question of whether TRIP12 can be validated as a gene associated with ASD." (PMID 33198194, 2020).
colorectal cancer (3 papers, 2021 to 2023). A primary or metastatic malignant neoplasm that affects the colon or rectum. "Our data demonstrate that TRIP12 is an essential mediator of TGFβ signalling in the intestine and warrants further evaluation of TRIP12 function in intestinal biology and in colorectal cancer in vivo." (PMID 37863914, 2023). "We previously showed that targeting TRIP12 enhances Taxol-induced cell death in colorectal cancer." (PMID 36672454, 2023).
hepatocellular carcinoma (3 papers, 2018 to 2021). A malignant tumor that arises from hepatocytes. "Unsurprisingly, overexpression of USP7 and TRIP12 has been found to be associated with poor prognosis in cancers with aberrant expression of p14ARF, such as hepatocellular carcinoma (HCC)." (PMID 29858610, 2018). "The TRIP12 result is consistent with previous reports that showed that knockdown of TRIP12 by shRNA does not affect USP7 levels in hepatocellular carcinoma cells." (PMID 30367141, 2018).
Clark-Baraitser syndrome (2 papers, 2024 to 2025). "Mutations in TRIP12 have been linked with several syndromic and non-syndromic neurodevelopmental deficits including Clark-Baraitser syndrome and intellectual disability with/without autism." (PMID 38985307, 2024).
cognitive deficits (2 papers, 2024 to 2025). "Trip12 has 3 known phospho-sites and 76 interactors; however, its mechanistic role in LIB-induced cognitive deficits in rTg4510 remain unclear." (PMID 38542311, 2024).
liver cancer (2 papers, 2020 to 2021). An epithelial or non-epithelial malignant neoplasm that arises from the liver. "More recently, studies in liver cancer found that the deubiquitinating enzyme USP7 stabilizes TRIP12, which leads to constitutive p14ARF ubiquitination and degradation, thereby promoting the growth of liver cancer cells." (PMID 33963176, 2021).
lung adenocarcinoma (2 papers, 2020 to 2021). A carcinoma that arises from the lung and is characterized by the presence of malignant glandular epithelial cells. "TRIP12 has also been found to have the highest frequency of mutations in lung adenocarcinoma patients, while frameshift mutations of TRIP12 are present in colorectal and gastric cancers with microsatellite instability." (PMID 33963176, 2021).
non-small cell lung carcinoma (2 papers, 2024). A group of at least three distinct histological types of lung cancer, including non-small cell squamous cell carcinoma, adenocarcinoma, and large cell carcinoma. "Moreover, circEPB41L2 blocks the progression and metastasis in non-small cell lung cancer by promoting TRIP12-triggered PTBP1 ubiquitylation." (PMID 38715012, 2024).
speech disorder (2 papers, 2023 to 2025). A term referring to disorders characterized by the disruption of normal speech. "This is, to the best of our knowledge, the first report linking TRIP12 c.3404A>T (p.Asp1135Val; rs778262518) to a neurodevelopmental phenotype (ASD and speech disorder)." (PMID 41465129, 2025). "Overall, this case expands the phenotypic spectrum of TRIP12-associated disorders by reinforcing that missense variants can present in a familial form with ASD and speech disorder, without physical features." (PMID 41465129, 2025). "This familial case further presents the phenotypic spectrum of TRIP12 missense variants and highlights that ASD and speech disorder may occur as isolated neurodevelopmental findings without syndromic features." (PMID 41465129, 2025).
autosomal dominant intellectual disability syndrome (1 paper, 2022). "Clark–Baraitser syndrome is a rare autosomal dominant intellectual disability syndrome caused by pathogenic variants in the TRIP12 (Thyroid Hormone Receptor Interactor 12) gene." (PMID 36430143, 2022).
BAFopathies (1 paper, 2022). "We have shown that when we assess just over 100 of the most differentiating probes, the EpiSignTM classifier can discern TRIP12 from 56 other neurodevelopmental disorder episignatures including those associated with BAFopathies." (PMID 36430143, 2022). "We demonstrated that the differentially methylated probes (DMPs) that were identified in TRIP12 overlapped with that of BAFopathies (~10%)." (PMID 36430143, 2022). "This analysis showed that TRIP12 is most closely related to the CSS9 (SOX11), BAFopathy (ARID1A, ARID1B, SMARCB1, SMARCA2, SMARCA4) and MRD23 (SETD5) episignatures." (PMID 36430143, 2022).
bladder urothelial carcinoma (1 paper, 2020). "In certain types of cancer, a high level of TRIP12 mRNA is associated with a shorter disease-free survival (i.e., bladder urothelial carcinoma, pancreatic adenocarcinoma), which suggests that the TRIP12 mRNA level could be a useful prognostic marker." (PMID 33198194, 2020).
breast tumors (1 paper, 2021). "Similarly, in GSE6532-GPL570, there is a significantly lower (COX p value = 0.03578; HR = 0.27(95% CI: 0.08–0.92)) probability of distant metastasis in high TRIP12 breast tumors as compared to low TRIP12 tumors." (PMID 33963176, 2021).
cervical squamous cell carcinoma (1 paper, 2018). A squamous cell carcinoma arising from the cervical epithelium. "Few mutations of TRIP12 have been described in cancers and in particular in HPV related SCCs as only 0.5% and 1.5% of head an neck squamous cell carcinomas (HNSCC) and cervical squamous cell carcinomas (CSCC) tested were found mutated in the COSMIC database." (PMID 29416628, 2018).
clear cell renal carcinoma (1 paper, 2014). A malignant epithelial neoplasm of the kidney characterized by the presence of lipid-containing clear cells within a vascular network. "The chimeras TRIP12->SLC16A14 and TFG->GPR128 have been found in cancer patients with clear cell renal carcinoma." (PMID 25133550, 2014).
Coffin–Siris syndrome 9 (1 paper, 2022). "We also demonstrate that TRIP12 is closely related to the Coffin–Siris syndrome 9 (CSS9) episignature, which is the result of variants in SOX11." (PMID 36430143, 2022).
colon cancer (1 paper, 2021). "Inhibition of FBW7 expression with either siRNA in HEK293T cells, or genetic knockout via CRISPR/Cas9 in HCT116 colon cancer cells, completely rescued MCL1 levels in TRIP12-silenced and TRIP12-knockout cells, respectively." (PMID 33824312, 2021).
esophageal cancer (1 paper, 2024). A primary or metastatic malignant neoplasm involving the esophagus. "Our study also firstly confirmed that TRIP12 was an important factor in the esophageal cancer progression." (PMID 38706891, 2024).
glioma (1 paper, 2020). A benign or malignant brain and spinal cord tumor that arises from glial cells (astrocytes, oligodendrocytes, ependymal cells). "The Human Protein Atlas indicates a heterogeneous expression of TRIP12 depending on cancer type with a high TRIP12 frequency in head-and-neck cancer, testis cancer, and glioma patients." (PMID 33198194, 2020).